GLO1 (glyoxalase I)
Diseases named in the same sentence as GLO1 in open-access papers (continued):
Sharing a sentence is not in itself a finding about the gene and the disease.
Hyperglycemia (45 papers, 2013 to 2025). An increased concentration of glucose in the blood. "In conclusion, our results show that hyperglycemia causes (i) a decrease in Glo1 and Glo2 enzyme content, (ii) decreased Kir4.1 protein expression levels, and (iii) downregulation of the functional Kir4.1 channel current." (PMID 41154170, 2025). "Partial loss of Glo1 resulted in obesity, hyperglycemia, dyslipidemia, and alterations in lipid metabolism in metabolic tissues in an age- and sex-dependent manner." (PMID 39896461, 2025). "Our study demonstrates that the modulation of Glo-1 underlying dicarbonyl stress leading to hyperglycemia preceding vascular complications correlates with the expression of VCAM and TXNIP in micro- and macrovessels." (PMID 37759966, 2023). "NF-κB antagonises the transcriptional activity of Nrf2; therefore, hyperglycaemia-driven or an inflammation-associated increase in NF-κB accounts for the reduced GLO1 expression." (PMID 35682865, 2022). "GLO1 activity was increased in retinal extracts from a mouse model that was protected from hyperglycemia-induced vasoregression (a hallmark of DR) by loss of TRPC (Transient Receptor Potential-Canonical) channels." (PMID 34440621, 2021). "MG concentration was increased in model hyperglycemia by increase in flux of glucose metabolism and concomitant increase in flux of MG formation, synergizing with decrease in Glo1 activity, linked to increased proteolysis." (PMID 33644826, 2021). "To confirm that the suppressive effect of glycine on the AGE/RAGE axis was associated with the observed improvement in Glo1 function, we incubated the HUVECs directly with 400 μM MG for 72 h to mimic the dicarbonyl stress induced by hyperglycemia." (PMID 30944692, 2019). "This dysfunction of HAECs likely contributes to vascular dysfunction and underlies links of hyperglycaemia and GLO1 to risk of CVD." (PMID 27898103, 2016). "It was proposed that hyperglycemia provokes a positive feedback loop in which increased dicarbonyl stress induces RAGE expression which causes a downregulation of GLO1 expression resulting in impaired detoxification of dicarbonyls." (PMID 24920125, 2014). "Our findings also underline the decisive role for GLO1 activity in preventing hyperglycemia‐induced kidney damage." (PMID 24920125, 2014). "Additionally, consistent with hyperglycemia and dampened glucose tolerance Glo1+/−, the liver-specific signatures are associated with fasting glucose, HbA1c and HOMA-IR in human GWAS." (PMID 39896461, 2025). "Protein expression and functional consequences of hyperglycemia: role of AG in Glo1, Glo2, and Kir4.1 protein expression, and in Kir4.1 channel function." (PMID 41154170, 2025). "The overexpression of Glo1 in bovine endothelial cells reduced intracellular hyperglycemia and the formation of AGEs, indicating that MGO is a major precursor in the formation of AGEs." (PMID 40722867, 2025). "The overexpression of GLO-1 in endothelial cell lines has increased the protection against a hyperglycemia-induced angiogenesis deficit by reducing MG." (PMID 38399319, 2024). "GLO-1 overexpression restored the proangiogenic capacity and has been reported to prevent vascular aging and reverse hyperglycemia-induced angiogenic defects in human endothelial cells, bone-marrow-derived stem cells and cardiac stem cells." (PMID 38399319, 2024). "The aim of this study was to explore any cross-talk between Glo-1 and markers of hyperglycemia and oxidative stress." (PMID 37759966, 2023). "MGO accumulation and AGEs formation in the state of dicarbonyl distress is a direct consequence of chronic hyperglycemia which perpetuates physiological insufficiency of the Glyoxalase system via reduced Glo-1 transcription and activity." (PMID 37759966, 2023). "Upregulation of Glo-1 reduced hyperglycemia-induced carbonyl stress, AGE accumulation, and oxidative stress in diabetic rats." (PMID 35872977, 2022).
Hyperglycemia (continued). "A previous remarkable finding was that this proinflammatory signaling mediated by SETD7 and activated by transient and persistent model hyperglycemia was inhibited by overexpression of Glo1." (PMID 33644826, 2021). "Glyoxalase activity is reported in vitro to promote pericyte survival under hyperglycemic conditions and retinal extracts from a mouse model protected from hyperglycemia-evoked vasoregression showed higher GLO1 activity." (PMID 33143048, 2020). "Glo-1 activity is highly correlated with insulin sensitivity, and hyperglycemia and insulin resistance were increased in Glo-1 knockout animals." (PMID 32825285, 2020). "In diabetic encephalopathy, the elevated levels of MG during hyperglycemia and the downregulation of Glo-1 induced by oxidative stress lead to a clear increase in advanced glycation end-products (AGEs)." (PMID 32982741, 2020). "Overexpression of Glo1 protected EDCs from the effects of hyperglycemia as EDCs stimulated proliferation of endogenous cells akin to normoglycemic WT EDCs." (PMID 31534514, 2019). "In this study, we explore the influence of the key methylglyoxal detoxification enzyme, Glo1, on chronic hyperglycemia induced EDC dysfunction." (PMID 31534514, 2019). "Given that hyperglycemia promotes the generation of toxic metabolites, the influence of the key detoxification enzyme glyoxalase 1 (Glo1) on chronic hyperglycemia induced heart explant-derived cell (EDC) dysfunction was investigated." (PMID 31534514, 2019). "Glo1 overexpression prevented chronic hyperglycemia from adversely influencing the ability of EDCs to promote myocardial function (p=ns compared to normoglycemic WT or normoglycemic Glo1 EDCs)." (PMID 31534514, 2019). "Although media conditioned by Glo1 mice EDCs demonstrated a reduced ability to stimulate tubule formation, Glo1 overexpression attenuated the anti-angiogenic effects of hyperglycemia." (PMID 31534514, 2019). "The effect of hyperglycemia on EDC-mediated vessel formation were abrogated when animals received EDCs from donors that over-expressed Glo1." (PMID 31534514, 2019). "In this study, we use a transgenic murine model of Glo1 overexpression to critically evaluate the effect of chronic hyperglycemia on EDC-derived EVs." (PMID 31534514, 2019). "Prior work using transgenic strains has shown Glo1 overexpression attenuates hyperglycemia-induced endothelial dysfunction, oxidative damage and renal damage 44-46." (PMID 31534514, 2019). "Overexpression of Glo1 reduces dicarbonyl stress and prevents chronic hyperglycemia-induced dysfunction by rejuvenating the production of pro-healing extracellular vesicles." (PMID 31534514, 2019). "MG is mostly produced during glycolysis, however, hyperglycaemia, hypoxia, ischemia, inflammation, and oxidative stress, while simultaneously inhibiting the activity of GLO1, leading to intra- and extra-cellular accumulation of MG and hence AGEs." (PMID 31792287, 2019). "Glo1 overexpression increased EV production by normoglycemic EDCs while attenuated the effects of chronic hyperglycemia on EV production." (PMID 31534514, 2019). "Overexpression of GLO1 also reduces hyperglycaemia-induced oxidative stress in diabetic rats and in cultured mouse renal mesangial cells." (PMID 29783710, 2018). "In the present study, we investigated the effects of gene modification by GLO1 lentivirus in the prevention and reversal of hyperglycemia‐induced D‐ADSC dysfunction." (PMID 28170200, 2017). "To develop further the link of increased MG levels in HAECs and vascular dysfunction, we investigated the effects of GLO1-knockdown in HAECs in high glucose concentration as a model of hyperglycaemia." (PMID 27898103, 2016). "As the cells were grown in normoglycaemic media before we provoked the maximum phenotype by switching to hyperglycaemia and GLO1-knockdown simultaneously." (PMID 27898103, 2016).
Hyperglycemia (continued). "Glyoxalase-I overexpression reverses hyperglycemia-induced angiogenesis defects in vitro and transgenic overexpression of glyoxalase-I in rats reduces vascular AGE formation and improves vasoreactivity." (PMID 25063693, 2014). "It was also shown that GLO1 overexpression in diabetic rats prevents hyperglycemia-induced formation of MG-derived AGEs in the neural retina, prevents Müller glia dysfunction, and protects against capillary degenerative pathology." (PMID 24733965, 2014). "Since glutathione is a necessary co-factor for GLO1, episodes of hyperglycemia or oxidant stress would also reduce the cellular capacity to convert MG to lactate." (PMID 24167592, 2013). "Hyperglycemia resulted in a tendency of mildly elevated levels of the oxidation product 8-oxo-2′-deoxyguanosine in the heart, an effect which was prevented in the GLO-1 overexpressing animals." (PMID 23899787, 2013). "Further experiments on the glyoxalase system (MG, AGES, AG, GLO1, and 2) during hyperglycemic conditions can provide new insight into the mechanism of combatting hyperglycemia with AG, and with other diamines and polyamines, and into increasing the health status of the CNS." (PMID 41154170, 2025). "Overall, this study suggested that GLO1, AG, or NAC may be promising candidate compounds for the treatment of angiogenesis dysfunction caused by hyperglycemia in diabetic ischemic stroke." (PMID 35035668, 2022). "Third, the -possibly mild- effects of these SNPs could be overshadowed by other conditions that affect Glo1 transcription/activity, such as hyperglycemia, inflammation, hypoxia, or oxidative stress." (PMID 33540757, 2021). "Similarly, overfeeding Danio rerio Glo1 KO resulted in increased MG levels in tissue inducing hyperglycemia, insulin resistance and alteration in the retinal blood vessels." (PMID 34440621, 2021). "Moreover, Glo-1 overexpression decreased the hyperglycemia-induced elevation of oxidative stress and AGEs levels in diabetic rats." (PMID 32982741, 2020). "In fact, Glo-1 overexpression could restore the increases in the levels of AGEs and RAGE caused by hyperglycemia in diabetic rats." (PMID 32982741, 2020). "In addition, Glo-1 overexpression reduces hyperglycemia-induced expression of reactive carbonyl stress, AGEs, and oxidative stress." (PMID 29849886, 2018). "In this study, we further investigated the influence of dicarbonyl stress on the composition and regulation of the ECM in a study of rat L6 myoblasts by employing a GLO1-specific knockdown under conditions of high glucose concentration to simulate hyperglycemia." (PMID 28241483, 2017). "Indeed, a physiological decrease of Glo1 transcription and activity occurs not only in chronic hyperglycaemia but also with ageing, during which MGO accumulation occurs." (PMID 28106778, 2017). "Conversely, inhibition of GLO1 with a specific GLO1 inhibitor, S-p-bromobenzylglutathione cyclopentyl diester (BBGSHCp2) led to accumulation of MG in low glucose concentration and dysfunction similar to that found in the hyperglycaemia model." (PMID 27898103, 2016). "Moreover, there is a complex interaction between RAGE and GLO1 gene expression in the context of hyperglycemia." (PMID 24920125, 2014). "GLO1 might be a key factor for detoxifying MG and protecting organs against IR injury, and may also prevent hyperglycemia-induced diabetic complications." (PMID 25333471, 2014). "This was not due to an upregulation of glyoxalase I activity; however, we cannot exclude the possibility that the Akita mice have developed alternative compensatory mechanisms to adapt to the dicarbonyl stress associated with hyperglycaemia." (PMID 32979176, 2020). "Drosophila Glo1 knockouts exhibited elevated MGO levels, increased insulin resistance, and greater weight gain, and developed hyperglycemia, although they remained viable." (PMID 40722867, 2025).
Hyperglycemia (continued). "Hyperglycemia, oxidative stress, inflammation, and exogenous sources of MGO all lead to elevated MGO levels and reduced glyoxalase 1 (Glo1) activity, and an MGO-Glo1 imbalance will lead to vascular dysfunction." (PMID 40458597, 2025). "This is an indication that Glo-1, VCAM and TXNIP are upregulated in hyperglycemia leading to oxidative stress, and mediate endothelial dysfunction, eventually causing vascular complications in T2DM." (PMID 37759966, 2023). "Glo-1 activity, as determined spectrophotometrically, and methylglyoxal were quantified using UPLC-MS/MS and the expression of representative markers of hyperglycemia and oxidative stress was performed using quantitative real-time PCR." (PMID 37759966, 2023). "In fact, hyperglycaemia, hypoxia, ischaemia, inflammation, and oxidative stress drive the production of MGO and yield, in combination with GLO1 blockade, intra- and extracellular accumulation of MGO and MGO-derived AGEs (MGO-AGEs)." (PMID 35682865, 2022). "Our results suggest that Glo-1 and TXNIP might be partners-in-crime mediating hyperglycemia and the oxidative stress-driven onset and progression of micro- and macrovascular complications in T2DM." (PMID 37759966, 2023). "Moreover, it has been demonstrated that the overexpression of GLO1 can reduce AGE formation in cultured endothelial cells and also improve hyperglycemia-induced impairment of angiogenesis in human microvascular ECs." (PMID 35035668, 2022). "In addition to normalising hyperglycaemia, the MGO/GLO1 balance must be properly managed during vascular complications in the kidney." (PMID 31388341, 2019). "In contrast to the angiogenic findings, hyperglycemia and Glo1 overexpression had no impact on the ability of EDC conditioned media to stimulate NRVM proliferation (BrdU+/cTNT+ cells)." (PMID 31534514, 2019). "Gene deletion of GLO1 is also embryonically lethal in mice whereas in Drosophila, GLO1 knockout animals displayed increased MG and recapitulated the progression of T2DM with obesity, insulin resistance and hyperglycemia." (PMID 30250846, 2018). "3-DG concentrations did not vary upon GLO1 knockdown, but increased significantly with hyperglycemia." (PMID 28241483, 2017). "Hyperglycaemia per se for the duration of 3 days did not induce the hyperglycaemic phenotype with the effects on GLO1 expression and activity shown by others in long-term culture experiments." (PMID 27898103, 2016). "Herein we found that dicarbonyl stress induced in ECs by model hyperglycemia activated three sensor pathways of the UPR, with the response recapitulated by Glo1 knockdown in normal glucose concentration and prevented in model hyperglycemia by overexpression of Glo1." (PMID 38199038, 2024). "At present, it is not known how and if Glo-1 interacts with other putative hyperglycemia-induced genes and how this interaction may play out in the onset and progression of micro- and macrovascular complications of T2DM." (PMID 37759966, 2023). "Hyperglycemia alone was not able to induce the effects seen with GLO1 knockdown." (PMID 28241483, 2017). "After 24-weeks of hyperglycemia, levels of GO and MGO were not statistically different in the cardiac tissue of the three groups, although overexpression of GLO-1 tended to decrease levels of MGO and GO." (PMID 23899787, 2013).
breast carcinoma (35 papers, 2009 to 2025). "For example, proteomic studies of breast cancer revealed that overexpression of GLO1 was significantly associated with the grading of breast cancer." (PMID 40352588, 2025). "The results of the present study demonstrate an association between GLO-1 overexpression and advanced cancer stages, including breast cancer." (PMID 40727469, 2025). "For the first time, our methylome analysis pointed to major alterations in the epigenome associated with decreased GLO1-mediated detoxification in breast cancer cells." (PMID 36998085, 2023). "For breast cancer patients, high expression of Glo1 was associated with poor survival, with HR = 1.82 (logrank p < 0.001, n = 683)." (PMID 34790575, 2021). "For HER2-negative breast cancer, high expression of Glo1 was associated with poor survival, with HR = 2.02 (logrank p < 0.001, n = 531)." (PMID 34790575, 2021). "GLO1 has been reported to be overexpressed in several human cancer cell lines including leukemia, melanoma, prostate cancer, and breast cancer cells and has been implicated in cancer progression and drug resistance." (PMID 34742347, 2021). "In this context, the present study investigated the resveratrol, curcumin and piperine effects on oestrogen receptor-positive MCF-7 breast cancer cells, associating them with GLO1 activity." (PMID 32721999, 2020). "In this scenario, the aim of this study was to investigate the effects of the bioactive compounds resveratrol, curcumin and piperine (R-C-P) on MCF-7 breast cancer cells and to associate them to Glyoxalase 1 (GLO1) activity." (PMID 32721999, 2020). "GLO1 depletion is associated with a global decrease of phosphatases expression in breast cancer cells." (PMID 30674353, 2019). "To examine Glo1 expression and mutation in breast cancer, we used two different datasets: the TCGA dataset, which also includes data from normal tissues, and the METABRIC dataset, which lacks data from normal tissues." (PMID 30559934, 2018). "Because Glo1 amplification often occurs in gastric and liver cancers, we examined the alterations in copy number and mutations in Glo1 in breast cancer tissue." (PMID 30559934, 2018). "In the present study, the frequency of AA genotype and A allele of GLO1 were significantly higher in the group of breast cancer patients compared to controls." (PMID 29321821, 2017). "The frequency of the A allele of GLO1 was significantly higher among advanced cases of breast cancer compared with less invasive tumors (63 vs 46.5%, p = 0.001)." (PMID 29321821, 2017). "We established a strong correlation between up-regulation of GLO1 mRNA and A allele of GLO1 with higher stages of breast cancer." (PMID 29321821, 2017). "To the best of our knowledge we are the first to analyze the effect of GLO1 C332C gene polymorphism on its mRNA expression and enzyme activity at different stages of breast cancer in Egypt." (PMID 29321821, 2017). "Increased risk of breast cancer was observed with the homozygous AA genotypes of GLO1 when compared with the CC genotype carriers [OR: 6.6(3.1-14), p < 0.001]." (PMID 29321821, 2017). "The frequency of GLO1 A allele was significantly higher in breast cancer patients compared to controls [OR: 2.8(1.9-4.1), p < 0.001]." (PMID 29321821, 2017). "GLO1 A allele was associated with increased risk of breast cancer [OR (95%CI)= 2.8(1.9-4.1), P < 0.001]." (PMID 29321821, 2017). "In addition, we collected multiple datasets and performed K‐M survival analyses and found that higher GLO1 expression levels were significantly associated with a more unfavorable prognosis in patients with breast cancer." (PMID 40492378, 2025). "In breast cancer, lung cancer, bladder cancer, and colon cancer, GLO1 gene amplification was significantly associated with poor survival outcomes, suggesting that GLO1 could be used as a biomarker for poor prognosis." (PMID 40352588, 2025).